DSP (desmoplakin)
Diseases named in the same sentence as DSP in open-access papers (continued):
Sharing a sentence is not in itself a finding about the gene and the disease.
idiopathic pulmonary fibrosis (12 papers, 2013 to 2025). Idiopathic pulmonary fibrosis (IPF) is a nonneoplastic pulmonary disease that is characterized by the formation of scar tissue within the lungs in the absence of any known cause. "DSP is associated with idiopathic pulmonary fibrosis, lung dysfunction, chronic obstructive pulmonary disease, interstitial lung disease, and advanced glycation end product receptor levels." (PMID 39192889, 2024). "rs2076295 in the DSP gene is associated with differential gene expression of idiopathic pulmonary fibrosis in human lung." (PMID 31324189, 2019). "The implication of genetic polymorphisms in SFTPA2, SFTPC, MUC5B as well as DSP (encoding desmoplakin) as risk factors for pulmonary fibrosis suggest that the integrity of the barrier function is critically important in maintaining lung homeostasis." (PMID 24391588, 2013). "Another study revealed 23 DSP variants associated with idiopathic pulmonary fibrosis (IPF)." (PMID 38750426, 2024). "DSP variants have also been associated with idiopathic pulmonary fibrosis, although these variants may be protective against COPD." (PMID 36698131, 2023). "Last, as variants in DSP are common to both COPD and pulmonary fibrosis, we applied injury models including cigarette smoke exposure, a risk factor for both diseases, and found that DSP in iAT2s mediates responses to wounding, profibrotic stimuli, and cigarette smoke injury." (PMID 35857525, 2022). "Furthermore, the lead COPD GWAS single-nucleotide polymorphism (SNP) at the DSP locus has also been associated by GWAS with risk for pulmonary fibrosis, another disease involving AT2 injury (but with an opposite direction of effect)." (PMID 35857525, 2022). "However, we observed a significant association of a DSP variant, previously reported in idiopathic pulmonary fibrosis, COPD and spirometric measures of lung function, with change in quantitative emphysema over time." (PMID 31324189, 2019). "In idiopathic pulmonary fibrosis (IPF), the G allele has been identified as the risk variant and associated with a decreased DSP RNA expression, resulting in a dysfunction in cell migration and the remodeling process in the lungs." (PMID 40076669, 2025). "The lung epithelial cell during idiopathic pulmonary fibrosis escalates desmoplakin (DSP) expression due to demethylation of its promoter." (PMID 35599845, 2022). "Accumulation of DSP increases cell-cell adhesion force and promotes lung fibrosis." (PMID 35599845, 2022). "Genetic variants associated with DSP have been implicated in both COPD and pulmonary fibrosis." (PMID 35857525, 2022). "Intriguingly, SNPs for DSP and FAM13A are associated with both COPD and pulmonary fibrosis but with opposite risk alleles, suggesting a potential mechanistic link between the two diseases and inviting further study to understand the contribution of these genes in particular." (PMID 35857525, 2022). "However, in the candidate region analysis, rs2076295 in the DSP gene, previously associated with COPD, lung function and idiopathic pulmonary fibrosis, was associated with change in %LAA-950 (β (SE) = 0.09 (0.02), P = 3.79e-05) and in ALD (β (SE) = − 0.06 (0.02), P = 2.88e-03)." (PMID 31324189, 2019).
melanoma (12 papers, 2014 to 2025). A malignant, usually aggressive tumor composed of atypical, neoplastic melanocytes. "In general, the hub genes, including KRT5, IVL, and DSP, and key pathways associated with melanoma metastasis defined in the present study may provide new insights into clinical melanoma treatment." (PMID 35054979, 2022). "It was shown that DSP functions as a tumor suppressor in cancer migration, whereas researchers also indicated that the deficiency of desmoplakin induced loss of the epithelial phenotype and acquisition of aggressive phenotype and thus facilitated melanoma metastasis." (PMID 35054979, 2022). "The results showed upregulation of NR1H3, NTHL1, and SNX1, and downregulation of DSP in melanoma compared to normal skin." (PMID 41573564, 2025). "Both JUP and DSP were identified to be upregulated in melanoma cell lines, where they significantly increase tumor burden, VEGF-A, reduced IL-33, and angiogenesis, thus emphasizing their PT roles." (PMID 37834160, 2023). "In the present study, the downregulation of the KRT5, IVL, and DSP expressions implied inhibitory effects of these genes in melanoma metastasis." (PMID 35054979, 2022). "The enrichment of these categories reflects the dysregulation of transcriptional programs typical of keratinocytes (e.g., SPRR1/2/3, KRT10/KRT16, LOR, IVL, EVPL, SCEL, TGM1/TGM3, CERS3, ACER1, DSP) and, above all, the epithelial crosstalk that influences melanoma biology." (PMID 41465101, 2025). "Overall, KRT5, IVL, and DSP might represent potential functions for the prevention and treatment of melanoma metastasis." (PMID 35054979, 2022). "In this study, we highlighted that KRT5, IVL, and DSP may serve as novel targets to suppress melanoma metastasis." (PMID 35054979, 2022). "The direct roles of desmoplakin (DSP) and peptidase inhibitor 3 (PI3) in melanoma metastasis are largely limited, though they are generally involved in cell-cell adhesion." (PMID 40722520, 2025). "It is noticeable that the functional characteristics of KRT5, IVL, and DSP in melanoma have not been fully explored, especially in melanoma metastasis." (PMID 35054979, 2022). "The explicit function and regulatory mechanism of DSP in melanoma metastasis are not yet understood." (PMID 35054979, 2022). "Colo38 melanoma cells were infected with Ad-FHIT and subsequently treated with DSP." (PMID 36289813, 2022). "We found LOR, EVPL, SPRR1A, FLG, DSP, and CSTA had been reported in previous studies on melanoma." (PMID 35003328, 2021).
gastric cancer (9 papers, 2002 to 2025). A primary or metastatic malignant neoplasm involving the stomach. "The establishment of the knockdown and overexpression models of DSP in gastric cancer have revealed that its overexpression inhibits gastric cancer cell proliferation and promotes apoptosis, whereas its knockdown showed the opposite effects." (PMID 41169522, 2025). "Moreover, Transwell assays revealed that DSP knockdown enhanced the invasion and migration of gastric cancer cells." (PMID 41169522, 2025). "Additionally, it has been confirmed through research that MIR4435-2HG has the ability to activate the Wnt/β-catenin signaling pathway by suppressing the expression of desmoplakin (DSP), thus promoting the growth and metastasis of gastric cancer." (PMID 37998733, 2023). "In gastric cancer, desmoplakin (DSP) is the most abundant desmosomal protein." (PMID 35784328, 2022). "The inhibition of another plakin protein, desmoplakin, has been reported to activate the WNT/β-catenin pathway and epithelial–mesenchymal transition in gastric cancer cells." (PMID 39052015, 2024). "MTSS1 and DSP are known tumor suppressor genes and are together with PPP1R14A, also methylated in lung-, colorectal- and gastric cancer." (PMID 24260260, 2013). "Overexpression and knockdown experiments revealed opposing roles for DSP and MIR4435-2HG, unmasking a cascade through which MIR4435-2HG binds to and inhibits DSP, leading to activation of WNT/β-catenin signaling and epithelial-mesenchymal transition in gastric cancer cells." (PMID 31484163, 2019). "We propose that the MIR4435-2HG/DSP/WNT axis serves as a critical effector of carcinogenesis and progression of gastric cancer, and could be exploited therapeutically to improve patients’ outcomes." (PMID 31484163, 2019). "However, to our knowledge, no other reports related to galectin 3, S100A10, desmoplakin, occludin, keratins 8, 14, myosin VI, tubulin beta 4 and calveolin-3 in gastric cancer have been published." (PMID 12402156, 2002).
dermatitis (7 papers, 2015 to 2023). An inflammatory process affecting the skin. "A different set of more severe human skin disorders, but with molecular defects that resemble our ninein-knockout, have been reported from patients with mutations in the genes encoding desmoglein 1 or desmoplakin, leading to desmosomal defects and to dermatitis." (PMID 30923192, 2019). "Notably, similar to mutated variants in this study, partial gene silencing and some of the known DSP mutations [p.R451G from arrhythmogenic cardiomyopathy and p.H586P from severe dermatitis, multiple allergies, and metabolic wasting (SAM) syndrome]20,21 also showed increased cell motility." (PMID 34815391, 2021). "A range of allergies have been linked to mutations in desmoplakin, as well as metabolic wasting (SAM) syndrome and severe dermatitis." (PMID 32411128, 2020). "Defects in desmoglein 1 (DSG1) or desmoplakin (DSP), structural desmosomal proteins, cause severe dermatitis, multiple allergies, and metabolic wasting (SAM) syndrome, a severe multisystemic disease resembling IPEX syndrome at least clinically." (PMID 32226610, 2020).
Myocardial fibrosis (6 papers, 2021 to 2025). "Transcript levels of the pro-inflammatory and pro-fibrotic genes were increased and myocardial fibrosis comprised ~25% of the myocardium in the DSP-deficient hearts." (PMID 36818425, 2023). "Based on the published literature, acute myocardial inflammatory episodes might be the proximal cause of myocardial fibrosis and progressive dysfunction in the presence of DSP mutations." (PMID 39336825, 2024). "Variants in desmoplakin (DSP) and filamin C (FLNC) have been shown to be associated with ring-like patterns of myocardial fibrosis which has been associated with worse outcomes." (PMID 38550947, 2023). "For example, the PVs in the DSP gene, encoding desmoplakin, are the classic causes of ACM but are also known to cause left-dominant ACM characterized by severe myocardial fibrosis." (PMID 34790974, 2021). "Myocardial fibrosis, assessed by determining CVF, expression levels of a dozen genes involved in fibrosis, and activation of the TGFβ1, was extensive, comprising about 25% of the myocardium, a finding that is in accord with the pro-fibrotic cardiomyopathy caused by the DSP mutations in humans." (PMID 36818425, 2023).
lung adenocarcinoma (5 papers, 2018 to 2024). A carcinoma that arises from the lung and is characterized by the presence of malignant glandular epithelial cells. "MiRNA hsa-mir-30a and lncRNA AC104472.1 constituted regulatory module for lung adenocarcinoma a with TPI1, KPNA2, MET, HSP90B1, P4HB, DSP, CDH1, and ENO1." (PMID 36138770, 2022).
Obesity (5 papers, 2008 to 2025). Accumulation of substantial excess body fat. "Introgressed alleles dominate at the MTCH2 locus, associated with obesity/fat tissue in humans, and the DSP locus, essential for the proper development of epidermal skin in amphibians." (PMID 34178108, 2021). "When administrated to rats with HFD-induced obesity, DSP reduced body weight gain, abdominal fat mass, and serum lipid profiles." (PMID 36432054, 2022). "In line with this, in a third cohort stratified by metabolic health status among individuals with obesity (MHO/MUO), DES, DSP, and SMOC2 again showed significantly higher gene expression in OVAT compared to SAT." (PMID 41275133, 2025). "In the current study, we validated the depot-specific gene expression of GJA1, DES, DSP, and SMOC2 in intra-individually paired SAT and OVAT samples from 78 individuals with obesity from our in-house cohort using quantitative PCR." (PMID 41275133, 2025). "Moreover, although non-significant, we observed the same effect direction for DES, DSP and SMOC2 among individuals without obesity (N = 31)." (PMID 41275133, 2025).
asthma (4 papers, 2008 to 2025). "This analysis revealed multiple genomic loci associated with COVID-19 severity with or without asthma comorbidity, including DSP, HIP1 and RP1 genes." (PMID 38750426, 2024).
familial hypercholesterolemia (4 papers, 2008 to 2025). An inheritable form of hyperlipidemia, in which there are excess lipids in the blood. "Four disease–associated genes in the proband presented VUS: APC, APOB, DSG2, and DSP, respectively associated with familial adenoma polyposis, homozygous familial hypercholesterolemia and hereditary cardiac disease." (PMID 30233642, 2018).
ventricular tachycardia (4 papers, 2022 to 2025). A disorder characterized by an electrocardiographic finding of three or more consecutive complexes of ventricular origin with a rate greater than a certain threshold (100 or 120 beats per minute are commonly used). "In an observational study of 74 patients with ACM, Eva Cabrera-Borrego reported that sustained monomorphic ventricular tachycardia (SMVT) occurring in those carrying DSP mutations presented as a right bundle branch block morphology originating from the inferolateral segment of the left ventricle." (PMID 40709201, 2025).
colorectal cancer (3 papers, 2010 to 2020). A primary or metastatic malignant neoplasm that affects the colon or rectum.
COVID-19 (3 papers, 2023 to 2025). A disease caused by infection with severe acute respiratory syndrome coronavirus 2. "In our study investigating 936 hospitalized patients with COVID-19, we identified an association between a decreased risk of death and the TG heterozygous genotype and the recessive model (TT + TG genotypes) in DSP rs2076295." (PMID 40076669, 2025). "The variant rs4960330, at locus 6p24.3 within DSP, is associated with severe COVID-19." (PMID 38750426, 2024). "This study aims to identify the association of FAM13A, DSP, TOLLIP, TERT, and THSD4 variants with severe COVID-19 and post-COVID-19 condition in a Mexican mestizo population." (PMID 40076669, 2025). "A recent investigation demonstrated elevated DSP levels in acute COVID-19 cases." (PMID 38750426, 2024). "In summary, according to our findings, the involvement of DSP, TERT, and THSD4 during the acute phase of COVID-19 is related to the inflammatory process, cell migration, cytokines release, and the adaptive and innate immune responses." (PMID 40076669, 2025). "The well-known variants in recognized genes related to pulmonary function worsening (THSD4 rs872471) and interstitial disorders (FAM13A rs2609255, DSP rs2076295, TERT rs2736100) are related to the severity and mortality of COVID-19 and lung performance in the post-COVID-19 condition." (PMID 40076669, 2025). "These biological routes, including those involving the FAM13A, DSP, TOLLIP, TERT, and THSD4 genes, have not been entirely studied in COVID-19 and post-COVID-19 condition." (PMID 40076669, 2025).
emphysema (3 papers, 2008 to 2021). "Additional investigation of the DSP gene, and improved genetic risk scores are likely to provide further insights into the disease progression in emphysema and COPD." (PMID 31324189, 2019). "DSP variants may be associated with longitudinal change in quantitative emphysema." (PMID 31324189, 2019). "Additional investigation of the DSP gene are likely to provide further insights into the disease progression in emphysema and COPD." (PMID 31324189, 2019). "However, in our candidate region analysis, we identified significant associations of a variant in DSP and a PRS based on spirometric measures of lung function with the annual change in emphysema in European ancestry." (PMID 31324189, 2019).
fibrosis (3 papers, 2020 to 2025). the formation of excess fibrous connective tissue in an organ or tissue in a reparative or reactive process. "We found that a tissue section from a 10-week-old wild- type C57BL/6J mouse has 2.5% cardiac fibrosis relative to the 9.7% cardiac fibrosis observed in a 10-week-old desmoplakin-deficient mouse heart, which shows more visible fibrosis across the ventricles." (PMID 39451648, 2024). "However, transgenic mice with cardiac-specific overexpression of mutant desmoplakin (Myh6:DSP-p.R2834H-FLAG) developed cardiac fibrosis and apoptosis, leading to ventricular dilation in combination with cardiac dysfunction and ultrastructural changes of the intercalated disc." (PMID 32670084, 2020).
Insulin resistance (3 papers, 2011 to 2025). Increased resistance towards insulin, that is, diminished effectiveness of insulin in reducing blood glucose levels. "This suggests that palmitate induced loss of DSP protein can further enhance insulin resistance through the Wnt/β-catenin signaling pathway." (PMID 22132232, 2011). "Insulin resistance is a common pathological feature of fatty liver and related ailments, whereas loss of DSP has been noted in liver carcinoma." (PMID 22132232, 2011). "Our findings suggest that DSP expression may be perturbed by palmitate and, along with insulin resistance, may play a role in palmitate induced cytotoxicity, and serve as potential targets for further studies on non-alcoholic fatty liver disease (NAFLD)." (PMID 22132232, 2011). "In the subcutaneous adipose tissue depot, gene expression of DSP and GJA1 was negatively correlated with Homeostatic Model Assessment for Insulin Resistance (HOMA-IR), indicating at a potential role in insulin sensitivity." (PMID 41275133, 2025). "Desmoplakin (DSP), CXADR, and PKP2 are novel biomarkers for the development of insulin resistance." (PMID 30678306, 2019).
meningioma (3 papers, 2012 to 2025). A generally slow growing tumor attached to the dura mater. "The meningioma derived cells of the meningothelial subtype retained their characteristic morphology and expression of histopathological markers vimentin, desmoplakin, and epithelial membrane antigen (EMA) in co-culture." (PMID 36289516, 2022). "Meningioma cells of all subtypes of tumors were positive for human epithelial membrane antigen (EMA) and vimentin staining and desmoplakin staining, and negative for markers of neural cell types such as GFAP for astrocytes and β-tubulin III for neurons (data not showed)." (PMID 22754374, 2012).
non-small cell lung carcinoma (3 papers, 2023 to 2024). A group of at least three distinct histological types of lung cancer, including non-small cell squamous cell carcinoma, adenocarcinoma, and large cell carcinoma. "In human non-small cell lung cancer, DSP has been reported to function as a tumor suppressor through inhibition of the Wnt/β-catenin signaling pathway." (PMID 37340002, 2023). "In addition, desmoplakin has been shown to act as a tumor suppressor by activating the WNT/β-catenin pathway in non-small cell lung cancer studies." (PMID 39052015, 2024). "DSP is a cell–cell adhesion molecule reported to have an AT activity in non-small-cell lung cancer (NSLC) by inhibition of the Wnt/β-catenin signaling pathway, followed by inhibition of cell proliferation, migration, and invasion and an increase in sensitivity to induced apoptosis." (PMID 37834160, 2023).
prostate carcinoma (3 papers, 2021 to 2025). A carcinoma that arises from epithelial cells of the prostate gland. "Proteins unique to the U-EVs of the GS 6–7 group included several keratins, corneodesmosin, the cell–cell adhesion protein desmoplakin, and uroplakin-2, which is a marker for urothelial and prostate carcinoma." (PMID 40725142, 2025).
squamous cell carcinoma (3 papers, 2006 to 2011). A carcinoma arising from squamous epithelial cells. "Microscopic analysis with fluorescence-labeled antibodies for DSP revealed high expression of membrane DSP in Squamous Cell Carcinomas (SCC)." (PMID 17217525, 2006). "As shown in a study with squamous cell carcinoma, inhibition of EGF (epidermal growth factor) using antagonists led to an increase in DSP protein levels." (PMID 22132232, 2011). "For instance, we found that desmoplakin, which has been reported to be up-regulated in squamous-cell carcinoma was found to be significantly (p ≤ 0.05) over expressed in the ETS of squamous-cell carcinoma samples, compared with adenocarcinomas and large-cell carcinomas." (PMID 20187940, 2010).